IL25 (interleukin 25)
Diseases named in the same sentence as IL25 in open-access papers (continued):
Sharing a sentence is not in itself a finding about the gene and the disease.
allergic asthma (33 papers, 2013 to 2025). A asthma with a basis in a pathological type I hypersensitivity reaction. "Indeed, IL-25 exerts a relevant pathogenic role in allergic asthma and virus-induced exacerbations of type 2 airway inflammation." (PMID 34572294, 2021). "IL-17E (IL-25) is key to regulating type 2 immune responses and driving inflammatory conditions like allergic asthma through IL-17RA and IL-17RB receptors." (PMID 40443529, 2025). "Using a mouse model of allergic asthma, Ballantyne and colleagues demonstrated that blockade of IL-25 leads to the reduction in clinical expression due to type 2 cytokine-induced allergic inflammation." (PMID 38541674, 2024). "In experiments in vitro, the percentage of ILC2s in peripheral blood from patients with allergic asthma was significantly greater and responsive to IL-33 and IL-25, leading to the production of higher levels of IL-5 and IL-13 than healthy controls." (PMID 36674744, 2023). "Inhibition of IL-25 signaling, e.g., by an IL-25 neutralizing antibody, diminishes allergic airway inflammation, airway hyperresponsiveness, and airway remodeling in mouse models of experimental allergic asthma." (PMID 37759430, 2023). "IL-25, also known as IL-17E, has been shown as a key mediator in allergic asthma, strongly expressed during allergic airway inflammation." (PMID 35615348, 2022). "Eosinophils from allergic asthma subjects were cultured with IL-25 and HDM to identify the co-stimulator molecules expression." (PMID 35615348, 2022). "The expression of IL-25 is up-regulated in nasal tissues from patients with allergic rhinitis (AR); stimulation of Th2 cells with IL-25 locally promotes IL-13 and IL-9 production, which contributes to the pathology of allergic asthma." (PMID 36119076, 2022). "IL-25 upregulated HLA-DR, PD-L1, and OX-40L expression on eosinophils from allergic asthma patients." (PMID 35615348, 2022). "IL-17E (also known as IL-25) is a key regulator of type 2 immune responses and driver of inflammatory diseases, such as allergic asthma, and requires both IL-17 receptor A (IL-17RA) and IL-17RB to elicit functional responses." (PMID 35863378, 2022). "Type 2 immune responses to allergen exposure play crucial roles in the pathogenesis of allergic asthma, which is initiated by epithelium-derived cytokines including IL-33, IL-25 and thymic stromal lymphopoietin (TSLP)." (PMID 33607992, 2021). "Pre-clinical experimental models of rhinovirus (RV)-induced exacerbations of allergic asthma have been used to test the eventual therapeutic efficacy of an anti-IL-25 monoclonal antibody (ABM125)." (PMID 34572294, 2021). "In our results, IL-13 and IL-25 protein in the lung were upregulated by inhaled as compared to intranasal OVA challenge in OVA-induced allergic asthma." (PMID 31823765, 2019). "Especially, IL-25 protein in the lung were upregulated by inhaled as compared to intranasal OVA challenge with increased IL-13 protein in OVA-induced allergic asthma." (PMID 31823765, 2019). "IL-25 was primarily responsible for airway epithelial ER stress and apoptosis in an allergic asthma model." (PMID 29784924, 2018). "The IL-25/IL-25R axis plays a crucial role in promoting the recruitment and proinflammatory function of eosinophils in allergic asthma." (PMID 30345318, 2018). "Taken together, we demonstrate that SIT is effective in allergic asthma and dependent on its depressive effect on the expression of IL-25, epithelial integrity damage, and epithelial ER stress." (PMID 29784924, 2018). "Similar to allergic asthma and CRS, atopic dermatitis has been associated with increased expression of TSLP, IL-25, and IL-33 in the skin." (PMID 26965110, 2016). "In patients with allergic asthma, plasma IL-25 levels are elevated." (PMID 41303221, 2025). "Furthermore, the intranasal administration of PN has been shown to activate the MAPKs pathway and induce the production of TSLP and IL-25 independently of the IL-1R1/MyD88 signaling in a mouse model of allergic asthma." (PMID 39199175, 2024).
allergic asthma (continued). "IL-25 plays a significant role in eosinophil activation in allergic asthma." (PMID 35615348, 2022). "Finally, two proteins were identified as more closely related to non-allergic asthma according to specificity analysis, namely IL-25 and LGALS3." (PMID 33936056, 2021). "Conversely, anti-IL-25 antibody reduces airway inflammation in animal models of allergic asthma." (PMID 29456832, 2018). "Based on these findings, we elucidated not only a novel mechanism that SIT treatment alleviates apoptosis induced by ER stress in airway epithelial by suppressing the production of IL-25, but also discovered a potential therapeutic candidate for allergic asthma." (PMID 29784924, 2018). "This point of view may have been triggered by the use of robust ILC2 induction models, such as administration of IL-25, IL-33, papain, and Alternaria to study these cells in the context of allergic asthma or dermatitis." (PMID 29250067, 2017). "Despite IL-33 and IL-25 being identified as important promoters of allergic inflammation in mouse models, the influence of these cytokines on the effector role of basophils in human allergic asthma needs to be further characterized." (PMID 26762527, 2016). "This study investigated the effect of IL-25 and IL-33 on basophils in a model of allergic asthma." (PMID 26762527, 2016). "Our findings indicate that the alarmin cytokines IL-33 and IL-25 increase basophil activation and migratory potential, and may pose as a novel therapeutic targets for the treatment of allergic asthma." (PMID 26762527, 2016). "There are numerous causes of this disorder, and recent evidence indicates that the alarmin cytokines IL-25 and IL-33 may play a key role in promoting allergic asthma." (PMID 26762527, 2016). "To determine whether IL-25 is essential for induction of allergic airway inflammation, we subjected IL-25-deficient (Il25-/-) and littermate wild-type mice to allergic airway inflammation induced by HDM, the most common allergen of allergic asthma in Chinese patients." (PMID 35615348, 2022). "IL-22 has been shown to contribute to allergic asthma during the sensitization phase and to promote lung immunopathology during fungal allergy, but it can also inhibit antigen-induced eosinophil airway inflammation through inhibition of IL-25, of IL-10, or during the challenge phase." (PMID 25860963, 2015). "In non-allergic asthma, the airway inflammation was mediated by group 2 innate lymphoid cells (ILC2), a class of non T and non B cells that activated by epithelial-derived IL-25 or IL-33." (PMID 39342146, 2024). "We also found that IL-25 treatment upregulated cell surface expression of HLA-DR, PD-L1, and OX40L on eosinophils in peripheral blood from allergic asthma patients." (PMID 35615348, 2022). "Finally, two proteins (IL-25 and LGALS3) were identified as being more related to non-allergic asthma according to the specificity analysis performed." (PMID 33936056, 2021). "We evaluated the levels of IL-33, IL-25 and TSLP, which are the upstream cytokines of ILC2s, in mice BALF when the airway epithelium was exposed to allergens to confirm whether Renifolin F inhibited OVA-induced allergic asthma by acting on ILC2s in mice." (PMID 35744915, 2022). "Moreover, it could be released from AEC in response to virus-induced injury (together with other Th2-promoting cytokines such as IL-25 and TSLP) and might thus help to drive airway inflammation in acute exacerbations of allergic asthma." (PMID 25264520, 2014).
breast cancer (30 papers, 2015 to 2024). A primary or metastatic malignant neoplasm involving the breast. "The primary aim of this study was to explore the potential correlation between IL-25, an endogenous factor secreted by tumor-associated fibroblasts (TAFs), and the inhibition of metastasis in 4T1 mammary tumors in mice." (PMID 37765074, 2023). "Additionally, administration of a synthetic compound able to induce IL-25 production by tumor associated fibroblasts suppressed growth of mammary tumor metastases in mice." (PMID 33244315, 2020). "Considering that death in human breast cancer patients are usually caused by tumor metastasis, a combination of tumor surgery with anti-IL-25 treatment may therefore provide a novel useful approach in treatment of human breast cancer." (PMID 27909985, 2017). "Study found that c-RAF, ERK and p70S6 kinases were phosphorylated in breast cancer cells following treatment with IL-25 in several breast cancer cell lines (T47D, MCF7, BT-20, and IJG-1731)." (PMID 37005677, 2023). "In breast cancer, the antitumor effects of IL-17E, also namely IL-25 and a member of IL-17 family, were induced by apoptosis and infiltration of eosinophils and B cells via binding to IL‐25R on tumor cells." (PMID 35783266, 2022). "Studies have shown that IL-25 plays a direct role in cancer cells and affects the development of breast cancer." (PMID 36119529, 2022). "Previous studies suggested that IL-25 played a direct role in cancer cells to affect the development of breast cancer." (PMID 31296243, 2019). "To further study the role of IL-25 in breast cancer development, we utilized a mouse model of spontaneous breast tumor - the MMTV-PyMT transgenic mouse." (PMID 27909985, 2017). "This IL-25 secretion was shown to play a key role in the Q2-3-mediated anti-metastatic activity in mouse mammary tumor models." (PMID 28674499, 2017). "IL-25 can be expressed by normal human breast epithelial cells, and its level was found to be further elevated in human breast cancer biopsies in previous studies." (PMID 27909985, 2017). "In this work, we investigated the role of IL-25 in a widely used spontaneous breast cancer model, the MMTV-PyMT transgenic mice with lung as the major metastasis site." (PMID 27909985, 2017). "In our study, we found that IL-25 was abundantly expressed in all four major types of human breast cancer patients, and both tumor cells and tumor-infiltrating cells expressed clearly high levels of IL-25." (PMID 27909985, 2017). "Taken together, our results suggest that the Q2-3-induced IL-25 secretion from fibroblasts plays a critical role in suppressing the growth activity of metastatic mammary tumour cells." (PMID 27089063, 2016). "In this study, our findings also indicate that the stromal fibroblasts in the mammary tumour microenvironment can express IL-25 which can in turn mediate an anti-metastatic effect on the companion tumour cells." (PMID 27089063, 2016). "In contrast, depletion of IL-25 attenuated the growth-suppressive effect of Q2-3-treated fibroblasts CM on mouse and human mammary tumour cells." (PMID 27089063, 2016). "With this artificial reconstruction approach, we compared the expression level of IL-25 in mouse and human fibroblasts, alone or in co-cultivation with test mammary tumour cells." (PMID 27089063, 2016). "Here we investigate the role of IL-25, an endogenous anticancer factor secreted from TAFs, in suppression of mouse 4T1 mammary tumour metastasis." (PMID 27089063, 2016). "Overexpression of IL-25R on the surface of malignant, mammary cells correlated with tumorigenic potential of breast cancer cells and poor prognosis, while IL-25/IL-25R pathway resulted in specific apoptosis in breast cancer cells." (PMID 26313265, 2015).
breast cancer (continued). "A tumor-infiltrating MMTV-PyMT tumor mouse model showed that tumor macrophages were the primary source of IL-25 and demonstrated the critical role of IL-25 in regulating the type 2 immune response by targeting Th2 cells in a breast cancer model, thereby promoting tumor metastasis." (PMID 38818476, 2024). "Conversely, others have found that IL-25 treatment can reduce subcutaneous tumour growth across a broad range of implanted cancer cell lines in immunodeficient mice, most likely through directly inducing apoptosis as shown in breast cancer cells." (PMID 37455828, 2023). "IL-25 could also initiate death signals in breast cancer cells by recruiting TRADD and FADD to induce caspase-mediated apoptosis." (PMID 37005677, 2023). "Additionally, the researchers conducted complementary studies to assess the potential suppressive effect of IL-25 secreted by fibroblasts on the growth activity of mammary tumor cells." (PMID 37765074, 2023). "Subsequently, IL-25 inhibited the proliferation of breast cancer cells." (PMID 37005677, 2023). "Encouragingly, IL25 monoclonal antibody XKH001 was the first IL25 inhibitor which was approved by the FDA in 2021 for the clinical trial of inflammatory associated diseases, and IL25 blockade inhibited lung metastasis in breast cancer." (PMID 35359953, 2022). "Intravenous or intraperitoneal administration of IL-17E (IL-25) in a variety of xenograft tumor models, including breast cancer, showed an antitumoral activity alone or in combination with chemotherapy or immunotherapy due to the induction of eosinophil expansion, through the production of IL-5." (PMID 34572273, 2021). "The interaction of IL‐25 with its receptor induces death signals in breast cancer cells in vitro." (PMID 34128588, 2021). "Ligation of IL‐25 to its receptor, IL‐17RB, on breast cancer cells also induces apoptosis." (PMID 34128588, 2021). "Together, our findings revealed that the secretion of IL-25 from TAFs could serve as a highly inducible therapeutic strategy for the control of mammary tumor metastasis." (PMID 28674499, 2017). "In addition, we found that IL-25 was broadly expressed in all the four major types of human breast cancer patients." (PMID 27909985, 2017). "For examples, IL-25 was shown to directly act on and induce apoptosis of breast cancer cells." (PMID 27909985, 2017). "Interestingly, tumor-infiltrating cells also exhibited copious IL-25 expression in the tumor, in all the four types of breast cancers examined." (PMID 27909985, 2017). "Altogether, our findings reveal that the release of IL-25 from TAFs may serve as a check point for control of mammary tumour metastasis and that phytochemical Q2-3 can efficiently promote such anticancer activities." (PMID 27089063, 2016). "In addition, IL-25 exhibited potent cytotoxic activity against breast cancer cells via IL-25R signaling pathways." (PMID 26840565, 2016). "To address whether IL-25 expression plays a key role in the anti-metastatic activity of Q2-3 on mammary tumour cells, we further employed an antibody-neutralization approach to deplete the in vivo IL-25 activity in the same 4T1 tumour resection model." (PMID 27089063, 2016). "IL-25 may also promote the malignant proliferation of breast cancer cells." (PMID 37005677, 2023). "Besides, IL25 also promoted breast cancer liver metastasis by inducing macrophage M2 polarization." (PMID 35359953, 2022). "Indeed, unlike IL-17B, IL-17E (or IL-25) causes caspase-mediated apoptosis of breast cancer cells and reduces colony formation of IL17RB-expressing breast tumor cell lines in vitro." (PMID 32373132, 2020). "The role of IL-25 in breast cancer has remained largely unknown." (PMID 27909985, 2017). "In this regard, they have shown that IL‐25 and IL‐17RB interaction phosphorylates c‐Raf, ERK, and p70S6 kinases in breast cancer cells (MCF‐7, IJG‐1731, and T47D cells lines)." (PMID 34128588, 2021).
breast cancer (continued). "IL-25 has been proved to influence the promotion of nonmelanoma skin cancer, colorectal cancer and breast cancer 9, 16-18." (PMID 38818476, 2024). "Therefore, administration of anti‐IL‐25 neutralizing antibodies decreased the IL‐4‐producing CD4+ T cells and M2 macrophages and reduced metastasis of breast cancer cells into lung tissue in the MMTV‐PyMT transgenic mice model." (PMID 34128588, 2021). "Furthermore, both IL-33 and IL-25 have been shown to promote angiogenesis which also contributes to metastasis, and genetic deletion of ST2 reduced VEGF expression and tumour burden in mouse breast cancer." (PMID 37455828, 2023). "In addition, a previous study found that IL25 expression in breast cancer was a positive correlation with infiltrating CD4+T cells and macrophages, whereas IL25 blockade decreased type 2 T cells and macrophages in the primary tumor microenvironments and inhibited lung metastasis." (PMID 35359953, 2022). "Among these endogenous anticancer factors, IL-25 (IL-17E) secreted by normal mammary epithelial calls has been reported to confer a specific anticancer effect on breast cancer cells, however, it has little or no cytotoxic effect on the non-malignant counterpart cells." (PMID 28674499, 2017). "Furthermore, IL-17A and IL-17E (IL-25) were involved in proliferation and survival of human breast cancer cell lines T47D and MCF7 as well as primary breast cancer biopsy cells IJG1731 and thereby promoted their resistance to the antimitotic chemotherapy agent docetaxel." (PMID 26783383, 2015).
atopic dermatitis (27 papers, 2013 to 2025). "Keratinocyte-derived alarmins, such as IL-33, TSLP, and IL-25 (IL-17E) that elicit Th2 cytokines responses by activating group-2 innate lymphoid cells (ILC2s) play an upstream pathogenic role in atopic dermatitis." (PMID 36578500, 2022). "IL-25 has been reported to be highly expressed in several skin inflammatory diseases, including atopic dermatitis, psoriasis, pyoderma gangrenosum, acute generalized exanthematous pustulosis, and cutaneous T-cell lymphoma (CTCL)." (PMID 35432341, 2022). "Recent findings on the role of IL-25 in the pathology of atopic dermatitis has shown that patients with moderate and severe atopic dermatitis tend to have higher IL-25 serum concentrations." (PMID 35406669, 2022). "First, to validate that introduction of Th2 related cytokines (IL-4, IL-13, and IL-25) can stimulate atopic dermatitis environment, we looked at differentially expressed genes with p-value < 0.005." (PMID 33806193, 2021). "The expression of Th2-inducing cytokines, such as TSLP (thymic stromal lymphopoietin), IL33, and IL25, is increased in atopic dermatitis, and other Th2-mediated disorders." (PMID 34571811, 2021). "Atopic dermatitis skin lesions demonstrate increased expression of IL-25 by keratinocytes and increased numbers of type 2 innate lymphoid cells (ILC2s) that express high levels of IL-25 receptor (IL-25R)." (PMID 32179159, 2020). "Results from a previous study demonstrated that periostin directly induces IL-25, a key cytokine in the initiation of the inflammatory cascade in atopic dermatitis via NF-κB activation in keratinocytes." (PMID 26890265, 2016). "In addition to production by ECs, dermal dendritic cells (DCs) have been reported to be a major source of IL-25 in atopic dermatitis (AD) patients, while IL-25 and IL-33-activated ILC2s in mouse skin promote AD-like inflammation." (PMID 25101088, 2014). "There is the possibility that direct contact of skin with these allergens could trigger signals to initiate a Th2 allergic response and that the epithelial cell-derived cytokines such as TSLP, IL-33, and IL-25 may drive the progression from atopic dermatitis to bronchial asthma." (PMID 33806376, 2021). "For atopic dermatitis, intelectin (ITLN) is a key factor for the expression of IL-25 in airway epithelial cells and aggravates allergic airway inflammation." (PMID 36119076, 2022). "TSLP-elicited ILC2 promotes allergic inflammation, whereas IL-25 and IL-33 are dispensable for this ILC2 response in an atopic dermatitis-like mouse model." (PMID 35432341, 2022). "Given increased levels of type 2 cytokines, IL-13, IL-4 and IL-5, in acute atopic eczema lesions and enhanced production of epithelial cytokines IL-33, IL-25 and TSLP, it is plausible that group 2 innate lymphoid cells contribute to the pathogenesis of atopic dermatitis." (PMID 25427661, 2014).